GSC (goosecoid homeobox)
Description:
Regulates chordin (CHRD). May play a role in spatial programing within discrete embryonic fields or lineage compartments during organogenesis. In concert with NKX3-2, plays a role in defining the structural components of the middle ear; required for the development of the entire tympanic ring (By similarity). Probably involved in the regulatory networks that define neural crest cell fate specification and determine mesoderm cell lineages in mammals.
Synonyms: GSC1; SAMS
Tractability: Small molecule: it has a binding pocket of medium quality.
Gene: Protein-coding gene on chromosome 14 (94,768,223 to 94,770,113, reverse strand). Ensembl gene ENSG00000133937.
Subcellular location: Nucleus
Subcellular location (Human Protein Atlas): Nuclear speckles; Nucleoplasm
Pathways (Reactome):
Developmental Biology: Formation of definitive endoderm; Germ layer formation at gastrulation; POU5F1 (OCT4), SOX2, NANOG repress genes related to differentiation
Gene Ontology:
Molecular function: sequence-specific double-stranded DNA binding; DNA-binding transcription factor activity, RNA polymerase II-specific; RNA polymerase II cis-regulatory region sequence-specific DNA binding; RNA polymerase II-specific DNA-binding transcription factor binding; DNA binding; DNA-binding transcription repressor activity, RNA polymerase II-specific
Biological process: neural crest cell fate specification; gastrulation; middle ear morphogenesis; regulation of transcription by RNA polymerase II; animal organ development; negative regulation of transcription by RNA polymerase II; regulation of DNA-templated transcription; tissue development
Cellular component: nuclear speck; nucleoplasm; chromatin; nucleus; transcription regulator complex
Genetic constraint (gnomAD): Loss-of-function variants: 13 observed, 14.77 expected, observed/expected ratio (o/e) 0.88, 90% interval 0.57 to 1.4. The synonymous counts are far from expectation, so gnomAD's model fits this gene poorly and the ratio says little. Missense variants: 382 observed, 293.34 expected, observed/expected ratio (o/e) 1.3, 90% interval 1.2 to 1.42. Synonymous variants: 199 observed, 137.57 expected, observed/expected ratio (o/e) 1.45, 90% interval 1.29 to 1.63.
Homologues: Orthologues: chimpanzee GSC (99% identical), macaque GSC (99% identical), pig GSC (98% identical), rat Gsc (97% identical), mouse Gsc (97% identical), dog GSC (96% identical), rabbit GSC (84% identical), tropical clawed frog gsc (74% identical), zebrafish gsc (66% identical), guinea pig GSC (60% identical). Paralogues in human: GSC2 (32% identical), VSX2 (28% identical), ARX (27% identical), ALX4 (23% identical), ALX3 (21% identical), PHOX2A (21% identical), PHOX2B (21% identical), ALX1 (21% identical), DMBX1 (21% identical), PAX6 (21% identical), PAX7 (21% identical), PITX2 (21% identical), and 38 more.
Diseases named in the same sentence as GSC in open-access papers:
GSC is named in the same sentence as 26 diseases in open-access papers, as found by Europe PMC text mining. Sharing a sentence is not in itself a finding about the gene and the disease. The quoted sentences say what the papers report.
breast carcinoma (2 papers, 2021). "Previous studies have suggested that Hhex regulated cell migration via upregulating ENG expression and downregulating GSC (a critical transcription factor for EMT) expression in breast cancer cells." (PMID 34321041, 2021).
breast tumor (1 paper, 2014). "The up-regulated genes include CTNNB1, GSC and TWIST1, encoding for transcription factors known to be activated during breast tumor metastasis, and AHNAK and AKT1, variously involved in tumorigenesis and cell motility." (PMID 24962430, 2014).
cryptorchidism (1 paper, 2017). The failure of one or both testes of a male fetus to descend from the abdomen into the scrotum during the late part of pregnancy. "Furthermore, it has been confirmed that microdeletion and homozygous predicted null mutations of GSC were involved in SAMS syndrome, which was characterized by unique rhizomelic skeletal anomalies, cryptorchidism (male), hypoplastic labia (female) and other urogenital anomalies." (PMID 28061432, 2017).
Fabry disease (1 paper, 2014). Fabry disease (FD) is a progressive, inherited, multisystemic lysosomal storage disease characterized by specific neurological, cutaneous, renal, cardiovascular, cochleo-vestibular and cerebrovascular manifestations. "Moreover, GSC-inhibition does not interfere with the synthesis of galabiosylceramide in the kidney and thus cannot abolish its accumulation in Fabry disease." (PMID 24992926, 2014).
glioma (1 paper, 2013). A benign or malignant brain and spinal cord tumor that arises from glial cells (astrocytes, oligodendrocytes, ependymal cells). "Thus, increasing GSC mRNA correlates with ascending grades of malignancy, which may be reflected by low endogenous ceramide levels in high-grade gliomas and increased GSC mRNA levels may characterize tumors that have a poor prognosis." (PMID 23667632, 2013).
Hepatic hemangioma (1 paper, 2014). A congenital vascular malformation in the liver composed of masses of blood vessels that are atypical or irregular in arrangement and size. "The positive nuclear expression in colon tissue, negative expression in normal liver tissue or in hepatic hemangioma indicated the specificity of the anti-GSC monoclonal antibody." (PMID 25343336, 2014).
liver cancer (1 paper, 2021). An epithelial or non-epithelial malignant neoplasm that arises from the liver. "As a consequence of ARID1A deficiency-induced conformational alteration, the dysregulation of some genes such as PMP22 and GSC, promoted the invasion capacity of liver cancer cells." (PMID 34689165, 2021).
microtia (1 paper, 2024). "Nevertheless, TCOF1 and HOXA2, in turn, cause microtia in a dominant manner, suggesting haploinsufficiency, while HSPA9 and GSC are in recessive mode of inheritance." (PMID 38594752, 2024). "Based on our findings, 64 cases (72.72%) were syndromic microtia [TCOF1 (43.75%), SIX2 (4.69%), and HSPA9 (4.69%)] and 24 cases (27.27%) were non-syndromic microtia [GSC exon 2 (25%), FANCB (16.67%), HOXA2 (8.33%), GSC exon 3 (8.33%), MARS1 (8.33%), CDT1 (8.33%)]." (PMID 38594752, 2024). "In the syndromic microtia group, the most common genes were TCOF1 (43.75%), SIX2 (4.69%), and HSPA9 (4.69%), while in the non-syndromic microtia group, the most frequently found gene was GSC exon 2 (25%), FANCB (16.67%), HOXA2 (8.33%), GSC exon 3 (8.33%), MARS1 (8.33%), and CDT1 (8.33%)." (PMID 38594752, 2024). "In the non-syndromic microtia group, the most frequently found gene was GSC exon 2 (25%; 6) and FANCB (16.67%); HOXA2, GSC exon 3, MARS1, CDT1 were found respectively in two (8.33%) cases." (PMID 38594752, 2024). "As reported in this review, the major gene disorder related to microtia phenotype is found in TCOF1 (32.82%; 28 cases), followed by GSC exon 2 (6.82%), FANCB (4.55%), SIX2 (3.41%), HSPA9 (3.41%) and CDT1 (3.41%) with each characteristic." (PMID 38594752, 2024). "We found 88 cases of genetic data related to microtia, including TCOF1 (31.82%), GSC exon 2 (6.82%), FANCB (4.55%), SIX2 (3.41%), HSPA9 (3.41%), and CDT1 (3.41%)." (PMID 38594752, 2024).
ovarian carcinoma (1 paper, 2015). A malignant neoplasm originating from the surface ovarian epithelium. "In recent years, a variety of molecular biomarkers in ovarian cancer have been identified, such as HE4, NPPB, and goosecoid homeobox." (PMID 25861644, 2015).
Pneumocystis pneumonia (1 paper, 2019). "The efficacy of GSC-1 as a therapeutic target may be limited, as the GMS-negative patient had worsening Pneumocystis pneumonia in the context of decreasing levels of Gsc1 expression and ascus burden." (PMID 31484742, 2019).
Sotos syndrome (1 paper, 2022). Sotos syndrome is a rare multisystemic genetic disorder characterized by a typical facial appearance, overgrowth of the body in early life with macrocephaly, and mild to severe intellectual disability. "In conclusion, we propose that NSD1 may participate in Sotos syndrome’s mechanism of action by regulating the function of lncRNA, inducing the down-expression of GSC, NDRG2 and SORBS1 and the up-expression of SFN and ZNF883." (PMID 35888078, 2022).
thyroid cancer (1 paper, 2020). "Investigating a similar focal hypomethylation in thyroid cancer cell lines, we discovered a previously unpublished binding site for the goosecoid homeobox protein (GSC), a known oncogene." (PMID 32920953, 2020).
triple-negative breast carcinoma (1 paper, 2018). An invasive breast carcinoma which is negative for expression of estrogen receptor (ER), progesterone receptor (PR), and human epidermal growth factor receptor 2 (HER2). "In this study, we show that SNAI2, a mediator of EMT highly expressed in triple-negative breast cancer, is upregulated in endocrine-resistant cells, whereas other EMT-associated transcription factors, such as SNAI1/3, TWIST1/2, ZEB1/2, FOXC2, and GSC, are unaltered." (PMID 29921289, 2018).
type 2 diabetes (1 paper, 2011). "We genotyped 1,486 subjects with type 2 diabetes from a Norwegian population-based cohort (HUNT2) for single-nucleotide polymorphisms (SNPs) located near the BNC2, SORCS1, GSC and WDR72 loci." (PMID 21294870, 2011).
infection (3 papers, 2019 to 2025). The state of being infected such as from the introduction of a foreign agent such as serum, vaccine, antigenic substance or organism. "The GSC-1 ectodomain induces a robust antibody response upon natural infection and immunization." (PMID 31484742, 2019).
GSC also shares sentences with these, for which no sentence is quoted: tumor (6 papers); Alzheimer disease (1); candidiasis (1); colorectal cancer (1); colorectal tumor (1); cyst (1); Hip dysplasia (1); hypoplastic labia (1); Insulin resistance (1); malignant glioma (1); unipolar depression (1).